MIR607 (microRNA 607)
Synonyms: hsa-mir-607; MIRN607
Gene: MicroRNA gene on chromosome 10 (96,828,669 to 96,828,764, reverse strand). Ensembl gene ENSG00000207976.
Gene Ontology:
Biological process: miRNA-mediated post-transcriptional gene silencing
Cellular component: RISC complex
Diseases named in the same sentence as MIR607 in open-access papers:
MIR607 is named in the same sentence as 1 disease in open-access papers, as found by Europe PMC text mining. Sharing a sentence is not in itself a finding about the gene and the disease.
MIR607 shares sentences with these, for which no sentence is quoted: tumours (1 paper).